ARLNC1 (androgen receptor regulated long noncoding RNA 1)
Synonyms: PRCAT47; LINC02170
Gene: Long non-coding RNA gene on chromosome 16 (80,826,074 to 80,892,682, reverse strand). Ensembl gene ENSG00000260896.
Diseases named in the same sentence as ARLNC1 in open-access papers:
ARLNC1 is named in the same sentence as 4 diseases in open-access papers, as found by Europe PMC text mining. Sharing a sentence is not in itself a finding about the gene and the disease. The quoted sentences say what the papers report.
prostate carcinoma (6 papers, 2019 to 2025). A carcinoma that arises from epithelial cells of the prostate gland. "For example, the DEG, LINC02532, was recently identified as a marker of radiosensitivity in clear cell renal carcinoma, while ARLNC1, decreased in our data, is associated with maintenance of androgen receptor signalling in prostate cancer." (PMID 36233808, 2022). "Gene expression analysis of prostate tissue revealed that BSE intake was associated with changes in the expression of 40 genes, including downregulation of α-methylacyl-CoA-racemase (AMACR) and androgen receptor-regulated long noncoding RNA 1 (ARLNC1), which are linked to prostate cancer." (PMID 40870788, 2025). "Similarly, androgen receptor regulated long noncoding RNA 1 (ARLNC1) is linked with prostate cancer progression." (PMID 31777593, 2019). "For instance, the lncRNA Androgen Receptor Regulated Long Non-coding RNA 1 (ARLNC1) regulates androgen receptor signaling and is one of the most differentially expressed androgen receptor-regulated genes in prostate cancer." (PMID 38095719, 2024). "In line with this, ARLNC1 silencing leads to inhibition of AR expression and suppression of AR signaling as well as of growth of prostate cancer." (PMID 37025585, 2023). "In fact, ARLNC1 has a role in the preservation of a positive feedback loop that induces AR signaling in the course of prostate cancer progression." (PMID 37025585, 2023). "In prostate cancer, AR activated the expression of several lncRNAs, such as ARLNC1, PCGEM1, and SOCS2-AS1, via binding to the androgen response element (ARE) sites in the lncRNA locus and promoting tumor progression." (PMID 32661324, 2020). "As a result, ARLNC1 promotes androgen receptor-dependent prostate cancer cell proliferation." (PMID 38095719, 2024).
cancer (1 paper, 2025). A tumor composed of atypical neoplastic, often pleomorphic cells that invade other tissues. "ARLNC1 (androgen receptor‐regulated long noncoding RNA 1) has been shown to exhibit a highly specific expression pattern in tissues of PCA and is strongly associated with AR signalling in cancer progression." (PMID 40259205, 2025).
ARLNC1 also shares sentences with these, for which no sentence is quoted: clear cell renal carcinoma (1 paper); tumor (1).